YAP1 (Yes1 associated transcriptional regulator)
Diseases named in the same sentence as YAP1 in open-access papers (continued):
Sharing a sentence is not in itself a finding about the gene and the disease.
thymoma (7 papers, 2021 to 2026). A neoplasm arising from the epithelial cells of the thymus. "In metaplastic thymomas the fusion partner is Yes associated protein 1 (YAP1), leading to YAP1::MAML2 fusion genes." (PMID 38067300, 2023). "Recently, it had been reported that there are high frequency Yes Associated Protein 1 (YAP1) - Mastermind Like Transcriptional Coactivator 2 (MAML2) fusions in an eight metaplastic thymomas cohort study, and the genetic alterations may be closely related to tumor occurrence or prognosis." (PMID 34354947, 2021). "Immunohistochemical analysis of YAP1 revealed stronger staining in normal thymic tissue compared to thymomas." (PMID 40649713, 2025). "Nuclear YAP1 expression was higher in thymomas compared to TCs (Mann–Whitney U test, p = 0.001) and in early tumor stage (Mann–Whitney U test, I/II versus III/IV, p = 0.023)." (PMID 40649713, 2025). "Metaplastic thymoma is a rare biphasic thymic tumor with indolent behavior and recurrent YAP1::MAML2 gene rearrangement." (PMID 38864046, 2024). "In metaplastic thymomas the fusion partner is YAP1, resulting in YAP1::MAML2 fusion genes fusing exon 1 or exons 1–5 on YAP1 with exons 2–5 on MAML2." (PMID 38067300, 2023). "While CRCT1 was found to be fused with MAML2 in mucoepidermoid carcinomas, as in mucoepidermoid carcinomas elsewhere in the body, YAP1 was identified as the fusion partner of MAML2 in metaplastic thymomas and KMT2A in type B2 and B3 thymomas." (PMID 38067300, 2023). "Moreover, when we compared the expression levels between B3 thymomas and TCs with the remaining histological types, B3 thymomas and TCs displayed a significantly lower nuclear YAP1 expression (Mann–Whitney U test, p = 0.010)." (PMID 40649713, 2025). "These two cases suggest that YAP1::MAML2 rearrangements may not only be found in pure metaplastic thymomas but also in more aggressive biphasic mediastinal tumors." (PMID 38067300, 2023). "In contrast, YAP1::MAML2 fusions were not identified in type A thymoma or micronodular thymoma with lymphoid stroma, another entity that may be included in differential diagnoses of metaplastic thymomas." (PMID 38067300, 2023).
urothelial carcinoma of the bladder (7 papers, 2015 to 2025). "In urothelial bladder cancer (UBC), YAP1 promotes KIF4A transcription, while KIF4A inhibits YAP1 phosphorylation, facilitating its nuclear translocation and activation, thus creating a self-amplifying oncogenic circuit." (PMID 41361459, 2025). "In urothelial bladder cancer (UBC), KIF4A establishes a positive feedback loop with the Hippo pathway core molecule YAP1, collaboratively driving tumour progression." (PMID 41361459, 2025). "We investigated the role of the Hippo effector YAP1 in the tumor immune microenvironment (TIME) of urothelial carcinoma of the bladder (UCB) and evaluated the efficacy of immunotherapy in the context of YAP1 signaling." (PMID 39630608, 2024). "However, the level of YAP1 expression was lower in ACC (adrenocortical carcinoma), BLCA (bladder urothelial carcinoma), UCEC (uterine corpus endometrial carcinoma) and UCS (uterine carcinosarcoma)." (PMID 34257617, 2021).
Alzheimer disease (6 papers, 2020 to 2026). A progressive, neurodegenerative disease characterized by loss of function and death of nerve cells in several areas of the brain leading to loss of cognitive function such as memory and language. "YAP1 is also expressed more highly in fusiform gyrus and temporal cortex from patients with Alzheimer’s disease, compared to controls." (PMID 34831369, 2021). "Importantly, YAP1 protein levels were significantly reduced selectively in the nuclear fractions of the brains of patients with Alzheimer's disease (AD) relative to normal control (NC) subjects." (PMID 42188696, 2026). "Yap1 has been confirmed as one of the pivotal genes in Alzheimer’s disease." (PMID 37549144, 2023). "miR-129-5p has been suggested to play roles in Alzheimer’s disease, potentially involving the regulation of autophagy, neuroinflammation, and neuronal cell death through targeting amyloid precursor protein (APP), high-mobility group box 1 (HMGB1), and yes-associated protein 1 (YAP1) genes." (PMID 38195609, 2024). "YAP1 and GJA1 act as related hub genes in Alzheimer’s disease." (PMID 37744228, 2023).
cervical squamous cell carcinoma (6 papers, 2014 to 2025). A squamous cell carcinoma arising from the cervical epithelium. "To further validate this multi-omics effect of YAP1 gene amplification at a pan-cancer level and specifically in CC, we analyzed data from The Cancer Genome Atlas Cervical Squamous Cell Carcinoma and Endocervical Adenocarcinoma (TCGA-CESC) cohort." (PMID 41256331, 2025). "YAP1 expression progressively increases across different grades of CIN, from CIN 1 to high-grade CIN 2, CIN 3, and eventually to cervical squamous cell carcinoma (CvSCC)." (PMID 41256331, 2025).
colitis (6 papers, 2021 to 2025). Inflammation of the colon. "Together, these data suggested that MSC therapy against colitis and T1D is dependent on chemical regulation of YAP1 in dimensional culture." (PMID 39897564, 2025). "Here, we show that intravenous infusion of 3D-preconditioned, extensively passaged MSCs serves as feasible therapeutic for both colitis and T1D, which is regulated by YAP1 expression." (PMID 39897564, 2025). "Overall, our findings suggest Selenow expression is key for efficient resolution of inflammation in experimental colitis that is mediated through the regulation of Egfr and Yap1." (PMID 37107231, 2023). "We hypothesized that Selenow ameliorates DSS-induced colitis by suppressing inflammation and promoting epithelial regeneration through mechanisms involving Yap1 and Egfr signaling." (PMID 37107231, 2023). "In the model group, the peak of YAP1 activity appeared on the 14th day, which was different from the previously reported peak of YAP1 in DSS-induced colitis on the 2nd–5th day." (PMID 34504536, 2021).
diabetes (6 papers, 2018 to 2025). "These collective findings strongly imply that Yap1 deficiency eradicated the kidney's innate resilience to diabetes-induced injury." (PMID 39608245, 2024). "We found that YAP1 activation increases with higher glucose levels, suggesting its role in triggering endothelial dysfunction in diabetes." (PMID 41450435, 2025). "Some studies have reported heightened YAP1 activity in podocytes during diabetes, noting a close correlation between increased expression of podocyte YAP1 and more severe renal pathological damage during DKD progression." (PMID 39608245, 2024). "Our current study for the first time demonstrated the consistent inactivation of YAP1 signaling in biopsy-approved human diabetic kidney, cultured HK-2 cells exposed to HG and PA, and tubule cells from DKD mice induced by a HFD plus STZ injection." (PMID 39608245, 2024). "One of the central findings of our study is the observed inactivation of YAP1 in tubule cells among individuals with diabetes and its accompanying impact on maintaining MQC homeostasis." (PMID 39608245, 2024). "Developing YAP1 inhibitors or modulators as part of a treatment regimen for diabetes could potentially reduce the incidence or severity of DR, offering a substantial benefit over current therapies that mainly focus on the advanced stages of the disease." (PMID 41450435, 2025). "The diabetes-induced elevation in serum creatinine and UACR levels observed in CTL mice was notably exacerbated following the deletion of tubular Yap1." (PMID 39608245, 2024).
endometrial cancer (6 papers, 2019 to 2025). Primary or metastatic malignant neoplasm involving the endometrium (mucous membrane that lines the endometrial cavity). "We collected specimens and clinical data from 774 patients with endometrial cancer to analyze the correlation between YAP1 expression and prognosis." (PMID 37744228, 2023). "Interestingly, YAP regulates the pro-inflammatory response in endometrial cancer cells through NF-κB and IL-6 signals, both of which are key regulators of psoriasis inflammation, suggesting the potential role of YAP1 in psoriatic pathogenesis." (PMID 40108109, 2025). "The aim of this study was to explore the role of YAP1, a core molecular of HIPPO pathway, in the stemness of endometrial cancer and to reveal its influence on prognosis." (PMID 37744228, 2023).
ependymal tumor (6 papers, 2017 to 2024). A group of neoplasms which arise from the ependymal lining of the cerebral ventricles and from the remnants of the central canal of the spinal cord. "Presence of microvilli and tight junctions confirmed that YAP1 dysregulation and activation leads to the formation of ependymal tumours similar to the corresponding tumours seen in humans." (PMID 32404936, 2020).
epithelioid hemangioendothelioma (6 papers, 2019 to 2025). A low-grade malignant blood vessel neoplasm. "Beyond that, aberrant Hippo signaling can arise from chromosomal translocations involving YAP1 or WWTR1 (encoding TAZ) as in epithelioid hemangioendothelioma, another fusion gene‐driven soft‐tissue tumor." (PMID 30898787, 2019). "The rare vascular sarcoma epithelioid hemangioendothelioma (EHE) is defined by WWTR1 or YAP1 gene rearrangements that result in functional fusion proteins." (PMID 40819258, 2025).
gallbladder cancer (6 papers, 2020 to 2024). "In one study, Taurodeoxycholic acid was found to promote malignant progression of gallbladder cancer through activation of YAP1." (PMID 39834394, 2024). "A comprehensive analysis of our data revealed that NF1 protein could affect the stabilization and ubiquitination of YAP1, resulting in gallbladder cancer progression." (PMID 37147639, 2023). "In our study, YAP1 was first investigated in HOXA-AS2-knockdown gallbladder cancer cells." (PMID 36299503, 2022). "The effect of lncRNA HOXA-AS2 on gallbladder cancer cells may affect the downregulation of miR-6867-5p and further affect the role of YAP1." (PMID 36299503, 2022). "Taken together, our results suggest that key components of the Hippo-YAP1 signaling pathway are dysregulated in advanced gallbladder cancer and reveal that the inhibition YAP1 may be a candidate for targeted therapy." (PMID 32218280, 2020). "Therefore, HOXA-AS2 may affect the expression of YAP1 protein by regulating miR-6867, thereby inhibiting the Hippo signaling pathway and promoting the proliferation and metastasis of gallbladder cancer cells." (PMID 36299503, 2022). "In summary, we identified that key components of the Hippo-YAP1 signaling pathway are dysregulated in GBC and that high nuclear levels of YAP1 predict worse prognosis in patients with pT2 gallbladder cancer." (PMID 32218280, 2020).
skin cancer (6 papers, 2017 to 2025). "Most importantly, the analysis of online datasets indicated that high expression of VEGF-C, YAP1 and Slug was associated with survival rate in skin cancer patients." (PMID 27901498, 2017). "Taken together, these results demonstrated that the VEGF-C/VEGFR3 signaling pathway affects cell mobility, cancer stemness properties and progression by the regulation of Slug through YAP1 in skin cancer." (PMID 27901498, 2017). "According to our analysis of Oncomine datasets, we found that YAP1 was highly expressed in metastatic skin cancer tissues." (PMID 27901498, 2017). "Our study confirms that VEGF-C is a critical inducer of cancer stemness, metastasis and invasion in skin cancer through regulating YAP1 expression via KRAS/MAPK signaling." (PMID 27901498, 2017). "Consistent with previous findings, we further demonstrated that VEGF-C-mediated YAP1 expression increases Slug expression and contributes to the migration and invasion abilities of skin cancer cells." (PMID 27901498, 2017). "For now, it is still unclear whether YAP1 is involved in the VEGF-C/VEGFR3 signaling pathway in skin cancers." (PMID 27901498, 2017). "We further identify VEGF-C/VEGFR3-mediated YAP1 and Slug expression through KRAS/MAPK signaling in skin cancer." (PMID 27901498, 2017). "By treating skin cancer cells with an anti-VEGFR3 specific peptide, we show that suppression of VEGF-C/VEGFR3 signaling significantly reduces YAP1 and Slug expression and diminishes the migration, invasion and cancer stemness of the cells." (PMID 27901498, 2017). "Although it is known that males develop more skin cancer than females and that YAP1 is upregulated in many skin cancers, a direct connection between VGLL3 and YAP1 in skin cancer has not yet been identified." (PMID 40741215, 2025). "Consequently, these results indicate that VEGF-C regulates YAP1 and Slug expression via the RAS/MAPK pathway to enhance cell mobility and cancer stemness in skin cancer cells." (PMID 27901498, 2017). "None of the other skin tumors examined, including 24 squamous cell carcinomas, 32 basal cell carcinomas, 5 cutaneous adenocarcinomas, 9 Merkel cell carcinomas, and 27 seborrheic keratoses, showed any evidence of recurring YAP1 fusions, as was reported in previous studies." (PMID 37627947, 2023).
adrenocortical carcinoma (5 papers, 2016 to 2025). "Moreover, we evaluated in vitro the association between the Wnt/beta-catenin pathway and YAP1 in adrenocortical carcinoma cells." (PMID 27705928, 2016). "The LinkedOmics analysis revealed 923 co-expressed genes with YAP1 in adrenocortical carcinoma, LGG and PAAD." (PMID 34257617, 2021). "Recent works further demonstrated the crosstalk could be established by dual directions, as YAP1 was identified as a crucial promotor for the adrenocortical cancer progression by mediating the transcription activity of β-catenin." (PMID 40604818, 2025).
clear cell renal cell carcinoma (5 papers, 2018 to 2025). "Enolase-2 was increased in PSCs with CCK-BR-KO and has recently been found to promote ferroptosis and inhibit glycolysis in clear cell renal cell carcinoma by regulating Hippo-YAP1 signaling." (PMID 41373844, 2025). "Similarly, in clear-cell renal cell carcinoma (ccRCC), NAT10 acts through ankyrin repeat and zinc finger peptidyl tRNA hydrolase 1 (ANKZF1) to increase the nuclear localization of yes1-associated transcriptional regulator (YAP1), thereby driving tumor progression and lymphangiogenesis." (PMID 41316475, 2025). "The aim of the study was to determine by immunohistochemistry cellular localization and immunoreactivity levels of YAP1 and LATS1 proteins in paired sections of tumor and unchanged renal tissues of 54 clear cell renal cell carcinoma (ccRCC) patients." (PMID 29850494, 2018).
diffuse large B-cell lymphoma (5 papers, 2022 to 2024). "Few reports of a regulatory IGF-IR/YAP1 axis have been published so far: Zhou and colleagues reported an analogous mechanistic link in diffuse large B-cell lymphoma, demonstrating that IGF-IR inhibition decreased YAP1 expression and restrained the activation of YAP1 downstream targets." (PMID 35459264, 2022).
Hyperglycemia (5 papers, 2020 to 2025). An increased concentration of glucose in the blood. "Hyperglycemia was found to stimulate the expression and activity of DNA‐PKcs, which directly interacts with Yes‐Associated Protein 1 (YAP1), inducing its phosphorylation at Thr226." (PMID 40279648, 2025). "Induction of an active oncogene yki, the homolog of human Yap1, in the ISCs leads to malignant tumorigenesis in the gut and subsequent wasting of host organs, including ovary degeneration, lipid loss, muscle dysfunction, hyperglycemia, as well as mortality." (PMID 33117196, 2020). "Notably, the transfection of either YAP1ΔWW or His‐DNA‐PkcsΔKinase was able to alleviate hyperglycemia‐induced ferroptosis and cardiomyocyte damage, underscoring the pivotal role that the DNA‐PKcs/YAP1 interaction plays in the modulation of hyperglycemia‐associated ferroptosis." (PMID 40279648, 2025). "Collectively, these results underscore the functional significance of DNA‐PKcs‐dependent YAP1 phosphorylation in the pathogenesis of hyperglycemia‐induced myocardial injury." (PMID 40279648, 2025). "It provides insights into how inhibiting the DNA‐PKcs/YAP1/ferroptosis pathway could prove a valuable therapeutic strategy for treating hyperglycemia‐related myocardial dysfunction." (PMID 40279648, 2025). "We observed that hyperglycemia induced the translocation of YAP1 from the cytoplasm to the nucleus, an effect that could be inhibited by the deletion of DNA‐PKcs or HA‐YAP1T226A transfection." (PMID 40279648, 2025). "Strikingly, the administration of the YAP1 activator XMU-MP-1 showcased remarkable efficacy, counteracting these multifaceted events, even in the presence of persistent hyperglycemia and hyperlipidemia in diabetic mice." (PMID 39608245, 2024). "Further the investigation revealed that inhibition of the ERK 1/2 signaling cascade reduced YAP1/TAZ expression, suggesting a potential therapeutic strategy to mitigate hyperglycemia-induced cardiovascular damage and inflammation." (PMID 39764116, 2024). "Protein expression of the YAP1/TAZ pathway, known for its involvement in fibrosis and inflammation, was also upregulated under severe hyperglycemia." (PMID 39764116, 2024). "Functional assays further demonstrated that knockdown of YAP1 via shRNA (sh‐YAP1), in contrast to MST1 (sh‐MST1) or LATS2 (sh‐LATS2) knockdown, significantly alleviated hyperglycemia‐induced cardiomyocyte damage and the induction of ferroptosis." (PMID 40279648, 2025). "Intriguingly, in HL‐1 cells transfected with the HA‐YAP1T226D mutant, the deletion of sh/DNA‐PKcs did not prevent the hyperglycemia‐induced nuclear retention of YAP1." (PMID 40279648, 2025). "Notably, in hyperglycemia‐exposed HL‐1 cells, NU7441 effectively abolished DNA‐PKcs–induced YAP1 phosphorylation at Thr226." (PMID 40279648, 2025).